UGT1A1 (UDP glucuronosyltransferase family 1 member A1)
Diseases named in the same sentence as UGT1A1 in open-access papers (continued):
Sharing a sentence is not in itself a finding about the gene and the disease.
neutropenia (continued). "Patients with the UGT1A1*28 or UGT1A1*6 polymorphism were reported to have reduced UGT1A1 enzyme activity, elevated SN-38 concentration, and increased risk for severe diarrhea or neutropenia following initiation of irinotecan treatment." (PMID 38305868, 2024). "Accordingly, the incidence of AEs, including neutropenia, anemia, and diarrhea, increases for patients who are homozygous for the UGT1A1*28 polymorphism." (PMID 39330050, 2024). "Among them, only one patient with UGT1A1*28 mutation experienced neutropenia event (grade 3), indicating that the UGT1A1 polymorphism had a limit impact on neutropenia incidence in our study." (PMID 39300077, 2024). "The frequency of grade ≥3 neutropenia and febrile neutropenia in patients with UGT1A1 double variants was high (66.7% and 33.3%, respectively)." (PMID 36836140, 2023). "Although our results are based on a small number of patients, we believe that patients with UGT1A1 double variants require further attention to neutropenia, even with a reduced dose of initial nal-IRI." (PMID 36836140, 2023). "With relevance to cancer treatment, UGT1A1*28 or UGT1A1*6 homozygotes are low metabolizers of irinotecan and have an increased risk of severe neutropenia, requiring preventive dose adjustments." (PMID 36639636, 2023). "The best example pertains to the clinically actionable marker UGT1A1*28, which is associated with reduced UGT1A1 activity and irinotecan-induced severe neutropenia." (PMID 37108395, 2023). "Second, UGT1A1*6 polymorphism is recognized as a potential predictor of irinotecan-related severe neutropenia." (PMID 38138211, 2023). "The results of previous studies indicated that patients with UGT1A1 homozygous*28/*28 genotype are at a higher risk of developing neutropenia while on SG therapy, and therefore patients known to have UGT1A1*28 homozygosity should be monitored closely." (PMID 38027003, 2023). "There are differences between Caucasian and Asian populations in their frequencies of UGT1A variants, and UGT1A1*6 and UGT1A1*28 are reportedly strongly associated with severe neutropenia, especially among Asian and Caucasian patients, respectively." (PMID 36308049, 2023). "With regard to the UGT1A1*6 polymorphisms, a meta‐analysis showed that patients homozygous for UGT1A1*6 had a high risk (OR = 2.95, vs genotype G/G) of severe neutropenia." (PMID 36308049, 2023). "It has been shown that delayed metabolism of SN-38 leads to enhanced irinotecan-induced toxicity and patients with these UGT1A1 genotypes are recognized as a higher risk population for irinotecan toxicity, such as neutropenia or diarrhea." (PMID 36836140, 2023). "In contrast, a meta-analysis reported an increased risk of neutropenia not only at medium or high doses of irinotecan, but also at lower doses, in patients with a UGT1A1*28/*28 homozygous genotype." (PMID 35207692, 2022). "In patients who experienced grade III–IV neutropenia, the UGT1A1*6, UGT1A7*3 and UGT1A9*22 polymorphisms showed significant associations only among those who received the weekly regimen (p = 0.015, p = 0.042, and p = 0.024, respectively)." (PMID 36239106, 2022). "The presence of the UGT1A1*6 allele also showed a significant association with grade III–IV neutropenia." (PMID 36239106, 2022). "A meta-analysis showed that Asians with lung cancer and UGT1A1*6 genetic polymorphism faced a higher risk of neutropenia and diarrhea after IRI chemotherapy." (PMID 35340156, 2022). "For example, low-activity UGT1A1 alleles (e.g., UGT1A1*28 and UGT1A1*6) are associated with an increased risk for severe or life-threatening neutropenia and myelosuppression during and after irinotecan administration." (PMID 36428799, 2022). "Several studies have suggested that the incidence of severe neutropenia is significantly higher in patients with double-variant UGT1A1*28 and *6 heterozygosity than in those with the wild-type genotype." (PMID 36114233, 2022).
neutropenia (continued). "Patients treated with irinotecan who are homozygous for the UGT1A1*28 allele are at greater risk of developing severe neutropenia after treatment." (PMID 35149777, 2022). "The most relevant finding is that the UGT1A1*28*28 genotype is associated with a substantial risk of grade ≥ 3 neutropenia despite an upfront irinotecan dose reduction." (PMID 35207692, 2022). "Associations between irinotecan toxicity and the UGT1A1*28/*28 genotype have been reported in cancer patients, suggesting a significantly higher risk of severe neutropenia." (PMID 35207692, 2022). "The risk factors for severe neutropenia in patients receiving mFOLFIRINOX were a low baseline white blood cell count and presence of heterozygosity for UGT1A1*28 or UGT1A1*6 polymorphism." (PMID 36114233, 2022). "In clinical use, heterozygous mutations of UGT1A1*6 and UGT1A1*28 are related to the risk and severity of vomiting, diarrhea, neutropenia and mucositis in patients with Pan-tumor and colorectal cancer post CPT-11 therpy." (PMID 35340156, 2022). "Previous Chinese studies also confirmed that, among esophageal cancer patients, both the UGT1A1*6 and UGT1A1*28 variants were related to severe neutropenia." (PMID 36239106, 2022). "Occurrence of severe neutropenia was inversely associated with dose reduction in UGT1A1*28 homozygous carriers (ORx10 unit = 0.62, 95% CI: 0.27–1.40, p = 0.249) and UGT1A1 heterozygous or wild-type patients (ORx10 unit = 0.87, 95% CI: 0.59–1.28, p = 0.478)." (PMID 35207692, 2022). "UGT1A1*28 is clearly associated with severe neutropenia and diarrhea in patients treated with irinotecan, mainly in homozygous patients." (PMID 36297516, 2022). "UGT1A1 activity is reduced in the UGT1A1 *28/*28 phenotype, which is found in approximately 10% of North American patients; this polymorphism leads to a higher risk of neutropenia and diarrhea with irinotecan therapy." (PMID 36038616, 2022). "In this study, we found that a low baseline WBC count and presence of heterozygosity for UGT1A1*28 or UGT1A1*6 polymorphism were significant independent risk factors for the development of severe neutropenia during treatment with mFOLFIRINOX." (PMID 36114233, 2022). "The UGT1A1*28 and intronic UGT1A1*6 (rs4148323) alleles increased the likelihood of neutropenia among Asian patients treated with the anticancer drug irinotecan, compared to the wild-type UGT1A1*1 allele." (PMID 34198586, 2021). "The model predicted less pronounced neutropenia in patients with wild-type genotype compared to the UGT1A1*28 allele following the approved single-agent dose of irinotecan (350 mg/m2)." (PMID 33733372, 2021). "The FDA-approved drug label states that UGT1A1*28 homozygotes have an increased risk of neutropenia, but limited data have been published regarding the association between UGT1A1 and sacituzumab govitecan toxicity." (PMID 33805415, 2021). "In Japanese patients, homozygosity for UGT1A1*28 or UGT1A1*6 and heterozygosity for both UGT1A1*6 and UGT1A1*28 are associated with severe irinotecan-related neutropenia." (PMID 33097971, 2021). "A phase I trial investigated the effects of UGT1A1 polymorphisms on the pharmacokinetics and toxicities (fatigue, nausea, vomiting, lethargy, neutropenia, and thrombocytopenia) of 48-hour continuous infusion belinostat." (PMID 33805415, 2021). "For irinotecan, UGT1A1*28 was significantly associated with neutropenia and diarrhea, particularly with doses ≥ 180 mg/m2, supporting the use of UGT1A1 to guide irinotecan prescribing." (PMID 33805415, 2021). "UGT1A1*6 and *28 alleles and their impact on the incidence of irinotecan toxicity (severe neutropenia and diarrhea) caused by elevated exposure to SN-38 have been the most extensively studied, with the majority of evidence focused on the UGT1A1*28 allele." (PMID 33805415, 2021).
neutropenia (continued). "Both UGT1A1*6 and UGT1A1*28 alleles have been extensively studied with regard to drug toxicity in particular to irinotecan, which can produce harmful side effects such as neutropenia and diarrhea." (PMID 32326111, 2020). "At the second cycle, patient carried UGT1A1*28 was a significantly higher risk of neutropenia than patients with homozygous wild type (OR 3.1, 95% CI 1.2–7.97; P = 0.017)." (PMID 32778670, 2020). "Within UGT1A1 gene the rs8175347 and rs10929302 (AA) have been implicated in toxicity, increased risk of diarrhea and neutropenia when treated with irinotecan in people with colorectal neoplasms." (PMID 31935801, 2020). "Although no firm conclusions can be drawn regarding safety in this small patient population, it is important to monitor patients with known UGT1A1 mutations for neutropenia." (PMID 33099898, 2020). "The UGT1A1 polymorphism has a significant relationship with irinotecan-induced toxicity, including both diarrhea and neutropenia." (PMID 32357899, 2020). "UGT1A1*6 and UGT1A1*28 polymorphisms are established as the most significant in the prediction of adverse drug reactions (ADR) occurrence such as neutropenia and diarrhea." (PMID 32664667, 2020). "The UGT1A1 gene polymorphism with irinotecan chemotherapy-associated diarrhea and neutropenia were closely related." (PMID 32264830, 2020). "Patients carrying both UGT1A1*28 and *6 were significantly associated with severe neutropenia at the first (P < 0.001) and second (P = 0.017) cycles." (PMID 32778670, 2020). "Our study clearly shows that UGT1A1 SH was associated with a higher incidence rate of severe hematological toxicity, mainly because of the increasing rate of neutropenia." (PMID 32666389, 2020). "In 2005, the U.S. Food and Drug Administration (FDA) informed that patients with homozygous UGT1A1*28 are at increased risk of severe neutropenia following initiation of irinotecan treatment." (PMID 32778670, 2020). "In recessive model, the random-effects model was used to analyze, and the result showed that UGT1A1*6 polymorphism was the risk of IRI-induced severe neutropenia (GG vs. AA+GA: OR = 0.40, 95% CI: 0.22–0.71, P=0.00)." (PMID 32936306, 2020). "The Food and Drug Administration (FDA) drug label for irinotecan includes therapeutic recommendations for UGT1A1*28 homozygous patients to reduce the risk of developing neutropenia [Irinotecan (CAMPTOSAR) drug label." (PMID 32695000, 2020). "In the second cycle, we found patients with UGT1A1*28 were at significant increased risk for grade 1–4 neutropenia compared with wild type patients (P = 0.011)." (PMID 32778670, 2020). "The UGT1A1*93 polymorphism also seems to be potentially significant for the occurrence of neutropenia following irinotecan treatment." (PMID 32664667, 2020). "Seven studies described the association between UGT1A1*6 polymorphism and severe neutropenia, respectively, and one study researched two different nations including Han and Xinjiang Uygur nationalities, thus eight researches were analyzed finally." (PMID 32936306, 2020). "At the second cycle, an association was observed between UGT1A1*28 and grade 1–4 neutropenia (OR 3.1, 95% CI 1.2–7.97; P = 0.017)." (PMID 32778670, 2020). "The combination of UGT1A1*28 and *6 showed a significant increased risk for all grades of neutropenia (P < 0.001) and severe neutropenia (P = 0.002) at first cycle." (PMID 32778670, 2020). "There was a higher instance of neutropenia in patients receiving nal‐IRI+5‐FU/LV who had mutations in UGT1A1 (homozygous for UGT1A1*6 [n =2] or heterozygous for UGT1A1*6 and UGT1A1*28 [n =1])." (PMID 33099898, 2020). "Grade 3 and 4 neutropenia occurred in 7 (29.1%) patients with wild-type UGT1A1 and 15 (55.6%) patients with UGT1A1 polymorphism." (PMID 32758288, 2020). "In a Japanese phase 2 trial of FOLFOXIRI plus Bev in mCRC patients, the frequency of neutropenia in patients with UGT1A1 *6 or *28 polymorphism is higher than that in patients with wild-type UGT1A110." (PMID 32345249, 2020).
neutropenia (continued). "For instance, the UGT1A1*28 polymorphism was established as a predictive marker of severe neutropenia, explained by a decreased UGT1A1 expression." (PMID 31506518, 2019). "In 2008, the Ministry of Health, Labour, and Welfare of Japan also warned increased risk of severe irinotecan-related neutropenia in Japanese patients carrying the UGT1A1*6 or *28 allele, and approved diagnostic test for UGT1A1 genotypes." (PMID 30016963, 2018). "In 2005, the USA Food and Drug Administration (FDA) warned that patients with UGT1A1*28/*28 genotype are at increased risk for neutropenia when irinotecan is used, and a lower starting dose of irinotecan was recommended for UGT1A1*28/*28 homozygotes." (PMID 30016963, 2018). "A significant association was found between UGT1A1 variants and neutropenia (P = 0.001) with higher risk for UGT1A1*28/*28 (OR, 3.75 [95% CI, 1.80–7.80]) than UGT1A1*1/*28 variants (OR, 1.66 [95% CI, 1.07–2.59]), both compared with the UGT1A1*1/*1 group." (PMID 29487697, 2018). "About 10% of patients with reduced UGT1A1 activity are at increased risk for diarrhea and neutropenia." (PMID 30154384, 2018). "The UGT1A1*28 polymorphism that results in TA repeating number alteration in the TATA box in the promoter can decrease the UGT1A1 expression and accounts for increased risk for irinotecan-induced neutropenia and myelosuppression." (PMID 30016963, 2018). "Patients who are homozygous for the UGT1A1* 28 allele (UGT1A1 7/7 genotype) are at increased risk for neutropenia (an abnormally low concentration of neutrophils in the blood)." (PMID 32467882, 2018). "Genetic variants in UGT1A1 have been reproducibly linked to neutropenia and diarrhea toxicity in various ethnicities and dosing regimens." (PMID 29793534, 2018). "Consistently, another metanalysis of Caucasian patients with metastatic colo-rectal cancer who received irinotecan found a 2-to-4-time increased risk of severe neutropenia and diarrhea in UGT1A1*1 6/6 carriers as compared with UGT1A1*28 7/7 carriers." (PMID 29861877, 2018). "The incidence rates of diarrhea and neutropenia are significantly higher, while median OS tends to be shorter in metastatic colorectal cancer patients receiving irinotecan with UGT1A1*28 heterozygous or homozygous mutations compared to the wild-type allele." (PMID 30453583, 2018). "The association of the UGT1A1*28 and *6 polymorphisms with an increased risk of developing irinotecan-induced neutropenia and diarrhea was confirmed." (PMID 30328952, 2018). "Physician must be aware of the potential hematological (mainly neutropenia and infectious disease) and digestive (mainly diarrhea) toxicities caused by irinotecan and especially when the patient presents a UGT1A1 ⁎28 homozygous allele." (PMID 29098099, 2017). "Then, the correlation of fglu(SN-38) and the reproduction frequency of the impact of UGT1A1*28 polymorphism on increasing the neutropenia was plotted using 30 sets of parameters." (PMID 28397089, 2017). "UGT1A1*28 heterozygotes (OR = 2.263, 95%CI 1.395–3.670), UGT1A1*28 homozygotes (OR = 5.910, 95%CI 1.138–30.672) and UGT1A1*6 homozygotes (OR = 4.737, 95%CI 1.946–11.533) were independent risk factors for severe neutropenia." (PMID 28637434, 2017). "Currently, individualised treatment of irinotecan can be tailored for patients who have been genotyped with the UGT1A1*28 allele, which predisposes them to higher risks of neutropenia." (PMID 28157715, 2017). "Out of all of the patients who received irinotecan-based chemotherapy, those who have more mutational alleles of UGT1A1*6 and UGT1A1*28 were found to be more likely to suffered severe toxicity (P = 0.001), especially severe neutropenia (P < 0.001)." (PMID 28637434, 2017). "The UGT1A1 ∗28 polymorphism has been linked to severe side effects, namely, neutropenia and diarrhea." (PMID 27563673, 2016).
neutropenia (continued). "In conclusion, the present results revealed that patients harboring one or more alleles had a higher risk of neutropenia at initiation of treatment, indicating the importance of testing for UGT1A1 genetic polymorphisms before commencing therapy." (PMID 26710796, 2016). "A systematic review analyzed the association between UGT1A1 ∗6 polymorphisms and irinotecan-induced neutropenia and diarrhea in Asian patients." (PMID 27563673, 2016). "The relationship between UGT1A1 polymorphisms and first-cycle neutropenia, reasons for treatment discontinuation, and time-to-treatment failure were evaluated." (PMID 26710796, 2016). "In a 2014 meta-analysis, sixteen studies were included in order to investigate the association of UGT1A1 polymorphisms and irinotecan-induced diarrhea and neutropenia." (PMID 27563673, 2016). "Metaanalysis of irinotecan pharmacogenetics studies show that there is an association between UGT1A1*28 homozygous genotype with neutropenia." (PMID 26808671, 2016). "Patients with UGT1A1 ∗6/ ∗6 genotype displayed an increased risk for severe neutropenia (OR, 4.44; 95% CI; 2.42–8.14; p < 0.001)." (PMID 27563673, 2016). "As a result, patients with UGT1A1 polymorphisms are more susceptible to toxicities such as neutropenia." (PMID 26710796, 2016). "Clinically, patients with either heterozygous UGT1A1*1/*28 or homozygous UGT1A1*28/*28 genotypes are more prone to severe irinotecan-associated toxicity, notably grade 3–4 neutropenia and/or diarrhea." (PMID 25577133, 2015). "Our pre-planned interim analysis of safety confirmed that the UGT1A1 homozygous and heterozygous genotypes were associated with a higher risk of severe neutropenia than the UGT1A1 wild-type genotype, consistent with the results of many previous studies." (PMID 25880011, 2015). "The UGT1A1 genotype was confirmed to be associated with increased risks of irinotecan-induced grade 3 or 4 neutropenia and diarrhoea." (PMID 25880011, 2015). "In conclusion, our study provides pivotal evidence supporting the association between the UGT1A1 genotype and an increased risk of irinotecan-induced severe neutropenia and diarrhoea in Japanese patients with colorectal cancer." (PMID 25880011, 2015). "Frequencies of these variants depend on ethnicity, with UGT1A1*28 being found more commonly in Caucasians and a higher frequency of UGT1A1*6 being found among Asians, both of which were associated with irinotecan-induced severe neutropenia and diarrhea." (PMID 26673747, 2015). "Irinotecan was associated with serious adverse events (especially neutropenia) particularly in patients with a variant UGT1A1*28, a polymorphism of UGT." (PMID 25884814, 2015). "The unacceptable discriminative power of the prediction model including only the UGT1A1 genotype suggests that our comprehensive approach incorporating non-genetic factors provides a more accurate prediction of the risk of severe neutropenia." (PMID 25880011, 2015). "In conclusion, the present study revealed that the UGT1A1*6/*28 and *6/*6 genotypes are associated with the occurrence of severe neutropenia in Japanese patients with gynecological cancer treated with low-dose CPT-11." (PMID 24932285, 2014). "In conclusion, the UGT1A1*6/*28 and *6/*6 genotypes were found to be associated with the occurrence of severe neutropenia in the low-dose CPT-11 regimen for gynecological cancers." (PMID 24932285, 2014). "Patients who are homozygous for the UGT1A1 TA7-allele have an increased risk for inrinotecan induced toxicity like neutropenia." (PMID 24587300, 2014). "This demonstrates the role of deficient UGT1A1 activity due to the presence of the homozygous variant genotype (UGT1A1*6/*28 or *6/*6) in the occurrence of severe neutropenia caused by the treatment of gynecological conditions with a low-dose CPT-11 regimen." (PMID 24932285, 2014). "In 2010, another meta-analysis concluded that UGT1A1*28/*28 genotype was associated with an increased risk of neutropenia in low doses as well." (PMID 24834123, 2014).